CD38 (CD38 molecule)
Diseases named in the same sentence as CD38 in open-access papers (continued):
Sharing a sentence is not in itself a finding about the gene and the disease.
tumor (continued). "The mechanism by which CD38 mediated PD-1/PD-L1 blockade resistance likely includes perturbation of adenosine receptor signaling in tumor microenvironment leading to immune modulation." (PMID 31214171, 2019). "Our group recently established the relevance of CD38 to HCC by identifying a correlation between CD38+ tumor-infiltrating leukocyte (TIL) density and improved patient survival." (PMID 31552039, 2019). "CD38, in particular, appears to play a significant role in the regulation of metabolism and immunomodulation of the tumor microenvironment." (PMID 31214171, 2019). "Taken together, CD38 inhibition is emerging as a potential therapeutic strategy for shaping the immunometabolome of host T cells in order to enhance immune response to tumor cells." (PMID 31214171, 2019). "Further studies of CCR5 on microglia will help to clarify the effect of CD38+HLA-DR+CD8+ T cells on the anti-tumor response." (PMID 31649684, 2019). "It has also been described that the CD38-NAD+ axis controls metabolic reprogramming of T cells in the tumor microenvironment and contributes to drug resistance plaguing PD-1/PD-L1checkpoint inhibitors." (PMID 31214171, 2019). "The constitutive presence of surface CD38 has also been described on another setting of tumor-derived exosomes." (PMID 31783629, 2019). "CD38 antibodies kill tumor cells via Fc-dependent immune effector mechanisms including complement-dependent cytotoxicity (CDC), antibody-dependent cell-mediated cytotoxicity (ADCC), antibody-dependent cellular phagocytosis (ADCP), and apoptosis." (PMID 31779273, 2019). "CD38 can be upregulated on tumor cells by all-trans retinoic acid, or by the histone deacetylase inhibitor panobinostat." (PMID 31379824, 2019). "For these reasons, the inhibition of CD38 has been proposed not only to specifically target CD38high immune suppressive cell populations (MDSCs, Treg), but also to improve tumor control via ACT therapy or using immunomodulatory drugs." (PMID 31402913, 2019). "In the present study, we sought to ascertain the in vivo expression of CD38 on macrophages from tumor tissues obtained from patients with HCC." (PMID 31552039, 2019). "Quantitative polymerase chain reaction and fluorescence-activated cell sorting further confirmed that tumor cells that developed resistance expressed elevated levels of CD38." (PMID 31861847, 2019). "These activated CD38+ TILs produce cytotoxic compounds and inflammatory cytokines to attack the tumor." (PMID 31861847, 2019). "It is currently unknown whether tumor-associated factors, including mutations in the antigen processing and presentation pathways, loss of antigen expression or insensitivity to T cell effector molecules are associated with resistance to CD38-targeting antibodies." (PMID 31783629, 2019). "For this reason, the most suitable tumor used for CD38 targeted therapies is the MM, still considered incurable." (PMID 31783629, 2019). "In vitro functional studies using THP-1 derived macrophages revealed CD38 expression to be associated with the M1 state, characterized by CD80 expression and secretion of TNFα and IL-6, all of which contribute to the anti-tumor immune response." (PMID 31552039, 2019). "Alternatively, researchers are also looking at selectively increasing the intensity of CD38 expression on the targeted tumor cells in order to maximize tumor-specific cytotoxicity and minimize on-target, off-tumor toxicity." (PMID 31379824, 2019). "For example, among the miRNAs downregulated by CD38 ligation, miR-193b functions as a tumor suppressor miRNA." (PMID 31118070, 2019). "CD38 was found up-regulated in MDSCs from various preclinical tumor models and cancer patients (neck cancer and non-small cell lung cancer)." (PMID 31130949, 2019). "An important aim of the inducible CAR-design is to effectively and rapidly control the on-target off-tumor mediated toxicities of high affinity CD38-CAR T cells." (PMID 29847570, 2018).
tumor (continued). "Our results thus indicate the feasibility of actively and timely controlling the CD38-CAR T cell activity in case of undesired toxicity associated with on-target, off-tumor effects." (PMID 29847570, 2018). "In concert with CD203 and CD73, CD38 contributes to the conversion of NAD+ to immunosuppressive adenosine in the tumor microenvironment." (PMID 30524421, 2018). "The anti-tumor effect of anti-CD38 mAbs is related to their ability to induce ADCC, CDC and ADCP of opsonized CD38+ cells." (PMID 30546360, 2018). "More importantly, they demonstrated that mice bearing MM xenografts treated with 213Bi-anti-CD38 mAb display a limited tumor growth via induction of apoptosis in tumor tissue, and a significantly prolonged survival compared to controls." (PMID 30546360, 2018). "Some of these nanobodies inhibited or enhanced CD38 enzymatic activity in a dose dependent manner and effectively targeted CD38 on human tumor cells in a mouse Xenograft model." (PMID 30459772, 2018). "This approach will provide another level of safety to already affinity optimized CD38-CAR T cells, but also increases the risk of tumor immune escape." (PMID 29847570, 2018). "It is currently unknown whether tumor-associated factors, such as mutations in the antigen processing and presentation pathways, loss of neoantigen expression, or insensitivity to T-cell effector molecules are associated with primary or acquired resistance to CD38-targeting antibodies." (PMID 30294326, 2018). "Blood HLA-DR+CD38+ CD8 T cells show expansion of tumor-infiltrating clones following anti-PD1 treatment." (PMID 30534127, 2018). "More importantly, we found that the removal of DOX results in a gradual elimination of the off-tumor hematotoxic effects of the high affinity CD38-CAR T cells, especially when DOX exposure dose was limited to 10ng/ml." (PMID 29847570, 2018). "Daratumumab-mediated CD38 reduction is a general phenomenon, which is also observed on non-tumor cells, such as normal B-cells, T-cells, NK-cells and monocytes." (PMID 30294326, 2018). "CD73, and more recently CD38, expression on tumor cells have been shown to confer resistance to anti-PD-1, as activation of T cells and PD-1 blockade upregulates the expression of A2AR, making these cells more susceptible to adenosine-mediated suppression." (PMID 30513816, 2018). "One study analyzed the combined effect of human anti-CD38 mAb Daratumumab and lenalidomide, a drug that is able stimulate the immune system and to induce apoptosis of tumor cells and inhibition of angiogenesis." (PMID 30546360, 2018). "Anti-CD38 CAR T cells demonstrated a potent anti-tumor effect when administered intravenously or intratumorally, thus suggesting that these cells efficiently migrate, infiltrate, and eliminate human MM tumors growing in their natural niche." (PMID 30546360, 2018). "From the safety point of view, our data clearly indicate that the removal of DOX will eventually result in the elimination of off-tumor toxicities of high affinity CD38-CAR T cells." (PMID 29847570, 2018). "It corresponds with last findings: expression of CD38 on tumor-infiltrating T cells correlates with longer survival of patients with carcinoma." (PMID 30713498, 2018). "Previous studies have relied upon CD138 as a plasma cell marker, however, as this molecule is also expressed on some tumor cells, we used CD38 to discriminate plasma cells within tumors." (PMID 29899747, 2018). "RMS cells were subdermally injected into WT or Cd38‒/‒ mice and primary tumor volume was measured at different time points." (PMID 30159123, 2018). "The CD38 antibodies also improve host-anti-tumor immunity by the elimination of regulatory T cells, regulatory B cells, and myeloid-derived suppressor cells." (PMID 30294326, 2018). "The results show that tumor outgrowth was significantly reduced in the Cd38‒/‒ mice compared to WT mice and that at 26 days post-injection the average tumor volume in Cd38‒/‒ mice was significantly smaller than in WT mice." (PMID 30159123, 2018).
tumor (continued). "Lastly, CD38 targeting can affect T cells via reducing ADO production thereby inhibiting anti-tumor immune responses of T cells." (PMID 30159123, 2018). "Using a carefully defined dose of DOX the CD38-CAR expression and thereby all associated effector functions decayed rapidly upon DOX removal, whereby minimizing the undesired off-tumor effects." (PMID 29847570, 2018). "WT and Cd38‒/‒ mice were injected with B16F10 cells and treated with vehicle or with the CD38 inhibitor K-rhein and tumor volume was assessed at the indicated time points." (PMID 30159123, 2018). "This feature points out the role of CD38 in the escape of tumor cells from the control of the immune system." (PMID 30546360, 2018). "All nanobodies also recognized native CD38 on tumor cells and lymphoid cells (T, B, and NK cells), and some of them still recognized tumor cells after opsonization with daratumumab, thus suggesting that these nanobodies recognized a different epitope." (PMID 30546360, 2018). "In this study we evaluated the feasibility of controlling the on-target, off- tumor effects of CD38-CAR T cells using a DOX inducible Tet-on CAR design." (PMID 29847570, 2018). "Accordingly the anti-tumor activity of ex vivo generated Th1/17 cells was dependent on increased NAD+ levels, which was associated with decreased expression of CD38." (PMID 30159123, 2018). "We tested the capacity of individual CD38-specific hcAbs to induce CDC to CD38-expressing LP-1 or CA-46 tumor cells in the presence of human serum as a source of complement." (PMID 30524421, 2018). "It is currently less clear why proteasome inhibitors combine well with CD38 antibodies, but this is probably related to the pleiotropic effects of proteasome inhibitors on both the MM cells and the tumor microenvironment." (PMID 30294326, 2018). "The anti-tumor effect of therapeutic strategy correlated with the expression level of CD38 on MM cell lines." (PMID 30546360, 2018). "It has been proposed that CD38 contributes to the immunosuppressive tumor microenvironment by hydrolyzing NAD+." (PMID 29636685, 2018). "Since antitumor response is naturally suppressed by Treg cells, it is possible that CD38 targeting will promote anti-tumor response by eliminating Treg cells." (PMID 30159123, 2018). "In vivo, fluorochrome-conjugated CD38 nanobodies efficiently reach CD38 expressing tumors in a rodent model within 2 hours after intravenous injection, thereby allowing for convenient same day in vivo tumor imaging." (PMID 29084989, 2017). "In a subcutaneous xenograft tumor model in nude mice, we examined the capacity of CD38-specific nanobodies to specifically target CD38-expressing tumor cells." (PMID 29084989, 2017). "It has been suggested that metabolites of NAD+ generated by CD38 in the tumor microenvironment can promote tumor growth and immunosuppression." (PMID 29084989, 2017). "Overexpression of ID3 gene correlated with decreased in CD38 expression and greater complexity of tumor cells (SSC)." (PMID 28245840, 2017). "Next, purified fluorochrome-conjugated monovalent anti-CD38 nanobodies were analyzed for binding to native CD38 on the cell surface of human tumor cells, NK cells and B cells." (PMID 29084989, 2017). "These three CD38 monocloncal antibodies were equally potent at inducing ADCC against CD38-expressing tumor cells." (PMID 31548533, 2017). "Taken together, in vitro and in vivo data indicate that FcγR‐mediated cross‐linking of daratumumab results in PCD of CD38 expressing MM tumor cells." (PMID 26864107, 2016). "Despite strong attenuation, the CD38-targeted, attenuated IFNα provided dramatic MM anti-tumor activity in various cell line and primary-derived tumor models." (PMID 27611189, 2016). "Anti-CD38-IFNα(att) strongly inhibited MM tumor cell proliferation, although it displayed approximately 20x lower potency relative to native IFNα(IC50s of 95.3 pM and 4.97 pM, respectively)." (PMID 27611189, 2016).
tumor (continued). "Treatment with anti-CD38-IFNα(att) generated the strongest anti-tumor response of all compounds tested in this model." (PMID 27611189, 2016). "Daratumumab binds a unique CD38 epitope and showed strong anti‐tumor activity in preclinical models." (PMID 26864107, 2016). "In human xenograft MM tumor models, anti-CD38-IFNα(attenuated) exerts potent anti-tumor activity in mice, inducing complete tumor regression in most cases." (PMID 27611189, 2016). "The robust, and in most cases curative, anti-tumor activity observed in vivo from anti-CD38-IFNα(att) therapy prompted further evaluation of this compound in mice bearing larger tumors." (PMID 27611189, 2016). "SCID mice injected with human MHCC-97 L HCC cells mice together with human CD19+CD24+CD38+ Bregs demonstrated markedly larger tumor growth at 6 weeks and increased serum IL-10 levels compared to SCID mice injected with HCC cells and CD19+CD24−CD38− non-Bregs." (PMID 27437104, 2016). "This was accomplished by engineering an attenuating mutation into the IFNα portion of an immunocytokine targeted to CD38 on MM tumor cells." (PMID 27611189, 2016). "We expanded upon this strategy by specifically targeting attenuated human IFNα to MM tumor cells via an anti-CD38 antibody and then tested its anti-tumor activity in vivo." (PMID 27611189, 2016). "Dexamethasone and the naked anti-CD38 control antibody exerted only a slight delay in NCI-H929 tumor growth compared to vehicle treatment (TTE 31 days, 26 days, and 18 days, respectively)." (PMID 27611189, 2016). "The results from all three xenograft models demonstrated that a strongly attenuated IFNα targeted directly to MM tumors via a CD38 antibody can induce improved, potent and long-lasting anti-tumor activity in vivo." (PMID 27611189, 2016). "Single chain antibodies against tumour associate antigens CEA, CD20 and CD38 have all been displayed on recombinant MV to facilitate targeted entry to epithelial carcinoma, non-Hodgkin’s lymphoma and myeloma cells, respectively." (PMID 27782084, 2016). "The CD38-targeted attenuated IFNα fusion protein, or “AttenukineTM”, identified as anti-CD38-IFNα(att), displayed a 10,000-fold greater specificity than native IFNα for CD38-positive (tumor) vs CD38-negative (normal) cells." (PMID 27611189, 2016). "We chose the MM tumor antigen CD38 as our target antigen because it is expressed at high levels on nearly all MM tumor cells and has limited normal tissue expression." (PMID 27611189, 2016). "CD38 is highly expressed on nearly all MM tumor cells and normal human plasma cells, with low expression on other normal BM precursor subsets." (PMID 27611189, 2016). "Accordingly, the tumor weights were significantly different in 213Bi-anti-CD38-MAb and PBS treated mice." (PMID 25576914, 2015). "Our data reveal that the production of ADPR by CD38 in response to tumor cells was ablated in Cd38−/− NK cells, indicating that CD38 was responsible for the production of ADPR in response to tumor cells." (PMID 25879940, 2015). "An original approach of this study derives from the recent use of the clinical availability of therapeutic anti-CD38 monoclonal antibodies (mAbs) in perturbing tumor viability and enzymatic functions in conditions mimicking what happens in vivo." (PMID 26393653, 2015). "All the CD38 activities in NK cells we described depend exclusively on the tumors contacted or the PME prepared from tumor cells." (PMID 25879940, 2015). "We show that TRPM2 is an ion channel located in the cytolytic granule, and co-migrates with CD38 to the immunological synapse upon tumor stimulation." (PMID 25879940, 2015). "This indicates that the interaction with tumor cells through cognate receptors on NK cells transmits signals for the activation of CD38's NAD glycohydrolase (NADase) to produce ADPR." (PMID 25879940, 2015). "In conclusion, we demonstrate that ADPR is produced by CD38, localized in cytolytic granules, upon tumor stimulation." (PMID 25879940, 2015).
tumor (continued). "As demonstrated by non-invasive bioluminescence imaging in two animals, tumor size remained constant after treatment with 213Bi-anti-CD38-MAb at days 34, 47, and 59 after tumor cell inoculation, whereas it drastically increased in PBS treated mice." (PMID 25576914, 2015). "The anti-tumor effect of 213Bi-anti-CD38-MAb correlated with the expression level of CD38 in each MM cell line." (PMID 25576914, 2015). "NK cells treated with 8-Br-ADPR, an ADPR antagonist, as well as NK cells from Cd38−/− mice showed reduced tumor-induced granule polarization, degranulation, granzyme B secretion, and cytotoxicity of NK cells." (PMID 25879940, 2015). "To elucidate the upstream signaling pathways of ADPR production by CD38 in tumor-induced NK cell activation, we determined [ADPR]i in NK cells following treatments with various agonistic and antagonistic agents." (PMID 25879940, 2015). "In conclusion, the present results support the role of CD38 in the genesis of tumor transformation of plasma cells." (PMID 24489445, 2013). "The consequence is that CD38 would be a component of one of the multiple strategies adopted by tumor to evade the immune response." (PMID 24489445, 2013). "Results from IVI and flow cytometry were confirmed by immunohistochemical staining of femura from tumor bearing NSG mice: the patient's kappa/CD38/CD138 triple-positive BM cells were well detectable in NSG mice 38 days after tumor cell inoculation." (PMID 24223204, 2013). "A similar distribution of CD38+ cells was seen in the second tumor within a vascular outgrowth from a pre-existing small vessel." (PMID 23308177, 2013). "In this pilot study, we observed increased levels of recently activated Tregs with tumor migrating ability (CD4+CD25hiFoxp3+CD127−CCR4+CD38+ cells) in patients when compared to controls." (PMID 24213326, 2012). "For example, in leukaemia, the ability to initiate new tumor growth resides in a rare phenotypically distinct subset of tumor cells that are defined by the expression of CD34+CD38- surface antigens and have been termed leukemic stem cells." (PMID 18492237, 2008). "The preclinical performance of the reported tracers was highly promising, both in absolute tumor uptake and ability to achieve high-contrast images rapidly, as highlighted by a CD38-targeting tracer that produced a ~ 96-fold tumor-to-muscle ratio within hours of injection." (PMID 41772598, 2026). "Furthermore, the expression of heat shock 70-kDa protein 1B (HSPA1B), a known tumor suppressor, was decreased in CD38+ NK cells from CRC patients but increased in the NK subset from RA patients." (PMID 42292426, 2026). "For example, gold NPs functionalized with anti-CD38 antibodies achieve laser-triggered photothermal inhibition of tumor growth, producing a 75% tumor mass reduction and preventing recurrence for 30 days, partly by suppressing NF-κB–dependent survival signaling." (PMID 41471085, 2025). "As MNs facilitate CD38‐EVs‐Dox to target tumour sites in tumour mice locally and spread through lymphatic channels and capillaries, further investigations are needed to understand the impact of our CD38‐EVs‐DoxMNs on tumour sites in various tissues like the parabrachial bone, lymph nodes and spine." (PMID 40317915, 2025). "As the hCD38 portion of this surrogate can only bind to the human CD38 expressed on the 38C13 tumors, these data suggest that hCD38-mAtt acts directly on the tumor cells but may also indirectly activate immune cell populations." (PMID 40315226, 2025). "To deliver CD38‐EVs directly to the tumour site in mice, we used dissolvable MNs for encapsulation." (PMID 40317915, 2025). "Notably, the enzymatic activity of CD38 contributes to the enhancement of tumorigenic properties within the tumor microenvironment." (PMID 40721446, 2025). "Moreover, CD38 was co-expressed with multiple CTCL tumor cell markers, providing evidence for CD38 expression in CTCL tumor cells." (PMID 39996780, 2025).